SCN1B (sodium voltage-gated channel beta subunit 1)
Description:
Regulatory subunit of multiple voltage-gated sodium (Nav) channels directly mediating the depolarization of excitable membranes. Navs, also called VGSCs (voltage-gated sodium channels) or VDSCs (voltage-dependent sodium channels), operate by switching between closed and open conformations depending on the voltage difference across the membrane. In the open conformation they allow Na(+) ions to selectively pass through the pore, along their electrochemical gradient. The influx of Na+ ions provokes membrane depolarization, initiating the propagation of electrical signals throughout cells and tissues. The accessory beta subunits participate in localization and functional modulation of the Nav channels. Modulates the activity of SCN1A/Nav1.1, SCN2A/Nav1.2, SCN3A/Nav1.3, SCN4A/Nav1.4, SCN5A/Nav1.5, SCN8A/Nav1.6, SCN9A/Nav1.7 and SCN10A/Nav1.8. [Isoform 2]: Cell adhesion molecule that plays a critical role in neuronal migration and pathfinding during brain development. Stimulates neurite outgrowth. Has no regulatory function on the SCN2A sodium channel complex.
Synonyms: ATFB13; BRGDA5; DEE52; EIEE52; GEFSP1
Tractability: Small molecule: a structure with a bound ligand is known; a high-quality ligand is known. Antibody: UniProt places it where antibodies can reach, with high confidence; its Gene Ontology location is reachable by antibodies, with high confidence; UniProt predicts a signal peptide or a membrane-spanning region. PROTAC: a small molecule that binds it is known.
Target class: Sodium channel auxiliary subunit beta family; Auxiliary transport protein
Safety:
Unwanted effects reported when the protein is acted on. In parentheses: how it was acted on, where the effect was seen, and who reports it.
agitation (inhibition, acute dosing; nervous system, respiratory, cardiovascular; source: Lynch et al. (2017))
cardiac arrhythmia (activation, acute dosing and inhibition, acute dosing; nervous system, respiratory, cardiovascular; source: Lynch et al. (2017))
coma (inhibition, acute dosing; nervous system, respiratory, cardiovascular; source: Lynch et al. (2017))
convulsions (activation, acute dosing; nervous system, respiratory, cardiovascular; source: Lynch et al. (2017))
decreased blood pressure (inhibition, acute dosing; nervous system, respiratory, cardiovascular; source: Lynch et al. (2017))
decreased cardiac conduction (inhibition, acute dosing; nervous system, respiratory, cardiovascular; source: Lynch et al. (2017))
decreased cardiac contractility (inhibition, acute dosing; nervous system, respiratory, cardiovascular; source: Lynch et al. (2017))
decreased gastrointestinal transit (inhibition, acute dosing; nervous system, respiratory, cardiovascular; source: Lynch et al. (2017))
decreased locomotor activity (activation, acute dosing; nervous system, respiratory, cardiovascular; source: Lynch et al. (2017))
decreased pain (inhibition, acute dosing; nervous system, respiratory, cardiovascular; source: Lynch et al. (2017))
decreased respiratory rate (inhibition, acute dosing; nervous system, respiratory, cardiovascular; source: Lynch et al. (2017))
decreased sweating (inhibition, acute dosing; nervous system, respiratory, cardiovascular; source: Lynch et al. (2017))
decreased urine excretion (inhibition, acute dosing; nervous system, respiratory, cardiovascular; source: Lynch et al. (2017))
decreased/increased convulsions (inhibition, acute dosing; nervous system, respiratory, cardiovascular; source: Lynch et al. (2017))
decreased/increased heart rate (inhibition, acute dosing; nervous system, respiratory, cardiovascular; source: Lynch et al. (2017))
dyspnea (activation, acute dosing; nervous system, respiratory, cardiovascular; source: Lynch et al. (2017))
increased heart rate (activation, acute dosing; nervous system, respiratory, cardiovascular; source: Lynch et al. (2017))
increased pupil diameter (inhibition, acute dosing; nervous system, respiratory, cardiovascular; source: Lynch et al. (2017))
increased QRS complex (inhibition, acute dosing; nervous system, respiratory, cardiovascular; source: Lynch et al. (2017))
Gene: Protein-coding gene on chromosome 19 (35,030,447 to 35,040,455, forward strand). Ensembl gene ENSG00000105711.
Subcellular location: Cell membrane (Isoform 1); Perikaryon; Cell projection; Cell projection, axon; Perikaryon (Isoform 2); Secreted
Pathways (Reactome):
Developmental Biology: Interaction between L1 and Ankyrins
Muscle contraction: Phase 0 - rapid depolarisation
Sensory Perception: Sensory perception of sweet, bitter, and umami (glutamate) taste
Gene Ontology:
Molecular function: protein binding; sodium channel regulator activity; sodium channel inhibitor activity; transmembrane transporter binding
Biological process: cardiac muscle cell action potential involved in contraction; cardiac muscle contraction; membrane depolarization; membrane depolarization during action potential; membrane depolarization during cardiac muscle cell action potential; membrane depolarization during Purkinje myocyte cell action potential; positive regulation of sodium ion transport; positive regulation of voltage-gated sodium channel activity; regulation of atrial cardiac muscle cell membrane depolarization; regulation of heart rate by cardiac conduction; sodium ion transmembrane transport; axon guidance; cardiac conduction; corticospinal neuron axon guidance; locomotion; neuronal action potential propagation; positive regulation of neuron projection development; regulation of membrane potential; regulation of ventricular cardiac muscle cell membrane repolarization; regulation of sodium ion transport; sodium ion transport
Cellular component: extracellular region; perikaryon; plasma membrane; voltage-gated sodium channel complex; cation channel complex; intercalated disc; node of Ranvier; T-tubule; axon; sodium channel complex
Genetic constraint (gnomAD): Loss-of-function variants: 11 observed, 25.63 expected, observed/expected ratio (o/e) 0.43, 90% interval 0.27 to 0.71. The upper end of that interval is the gene's LOEUF score, 0.71, which puts it in group 2 of 6, group 1 being the genes least tolerant of losing a copy. Missense variants: 204 observed, 294.75 expected, observed/expected ratio (o/e) 0.69, 90% interval 0.62 to 0.78. Synonymous variants: 106 observed, 116.28 expected, observed/expected ratio (o/e) 0.91, 90% interval 0.78 to 1.07.
Gene-disease validity (ClinGen):
ClinGen rates the evidence that SCN1B causes each of these diseases.
generalized epilepsy with febrile seizures plus (autosomal dominant): Definitive.
genetic developmental and epileptic encephalopathy (autosomal recessive): Definitive. A complex neurodevelopmental disorder characterized by a range of developmental delays and epileptic encephalopathy phenotypes.
Brugada syndrome 1 (autosomal dominant): Disputed. Any Brugada syndrome in which the cause of the disease is a mutation in the SCN5A gene.
Homologues: Orthologues: mouse Scn1b (96% identical), guinea pig SCN1B (94% identical), pig SCN1B (94% identical), dog SCN1B (94% identical), rat Scn1b (92% identical), rabbit SCN1B (91% identical), macaque SCN1B (89% identical), chimpanzee SCN1B (73% identical), tropical clawed frog scn1b (59% identical), zebrafish scn1ba (53% identical), zebrafish scn1bb (50% identical), zebrafish si:ch211-225p5.8 (42% identical). Paralogues in human: SCN3B (47% identical).
Diseases named in the same sentence as SCN1B in open-access papers:
SCN1B is named in the same sentence as 75 diseases in open-access papers, as found by Europe PMC text mining. Sharing a sentence is not in itself a finding about the gene and the disease. The quoted sentences say what the papers report.
epilepsy (46 papers, 2008 to 2025). A brain disorder characterized by episodes of abnormally increased neuronal discharge resulting in transient episodes of sensory or motor neurological dysfunction, or psychic dysfunction. "For example, mutations in the SCN1B can increase not only the risk of cardiac arrhythmia but also epilepsy." (PMID 39954672, 2025). "This hyperexcitability state likely explains why SCN1b null mice have severe seizures and why mutations in SCN1B are linked to epilepsy, cardiac arrythmia, and pain." (PMID 39947903, 2025). "SCN1B, encoding the β1 and β1B subunits of voltage-gated sodium channels, is implicated in epilepsy and arrhythmia syndromes." (PMID 39777262, 2024). "In fact, pathogenic variants of SCN1A/NaV1.1, SCN2A/NaV1.1, SCN3A/NaV1.1, SCN8A/NaV1.6, and SCN1B/β1, which are expressed in the central nervous system, are important causes of different types of epilepsies, including mild and severe forms." (PMID 37654020, 2024). "The proportion of benign epilepsy in patients with SCN9A, SCN11A, and SCN1B variants was relatively high, and the epilepsy control rate was higher than the rate of other variant types." (PMID 38174099, 2023). "Genetic variants in SCN1A, SCN2A, and SCN1B, encoding voltage-gated sodium channels, contributed to early-onset epilepsy." (PMID 36835631, 2023). "SCN1A, SCN2A, SCN3A, SCN8A, SCN9A, SCN11A, and SCN1B sodium channel gene mutations were intimately associated with epilepsy and displayed significant heterogeneity in pathogenesis and clinical symptoms." (PMID 38174099, 2023). "Voltage-gated sodium channels (VGSCs) play a critical role in generation of action potentials, SCN1A, SCN2A, SCN3A, SCN8A and SCN1B have been identified to be associated with a spectrum of epilepsy phenotypes and neurodevelopmental disorders." (PMID 36006933, 2022). "Abnormal SCN1B expression/function is linked to pathologies including epilepsy, cardiac arrhythmia, and cancer." (PMID 35752364, 2022). "Despite the highly similar electro-clinical phenotypes of the enrolled patients, the results obtained through NGS-based tests revealed possible variants in the SCN1A gene and four other epilepsy-related genes (SCN1B, SCN2A, SCN9A, and SCL2A1)." (PMID 35886038, 2022). "A female patient with hypotonia and abnormal development at birth as well as epilepsy by the age of 3 months was found to have the homozygous SCN1B variant p.Arg85Cys." (PMID 36291443, 2022). "SCN1B is another gene frequently found related to early-onset epilepsy and even linked to sudden unexpected death in epilepsy." (PMID 34877936, 2021). "Germline mutations with pathogenic or likely pathogenic effects at glycosylation sites are associated with cardiomyopathies (MYH7), cancer predisposition (CDH1), epilepsy (SCN1B), and others." (PMID 33834021, 2021). "Apart from seizure disorders, SCN1B variants also cause artrial fibrillation (type 13) and brugada syndrome (type 5)." (PMID 33841294, 2021). "For example, heterozygous mutations in extracellular domain of SCN1B and several additional mutations have all been associated with epilepsy." (PMID 32331418, 2020). "Five different genes that encode alpha subunits of sodium ion channels have been reported to have mutations that lead to epilepsy; these include SCN1A, SCN2A, SCN3A, SCN8A, and SCN9A, and epilepsy-inducing mutations have also been reported in SCN1B." (PMID 33102526, 2020). "SCN1B/β1 is the only β subunit whose genetic variants have been implicated in epilepsy." (PMID 37654020, 2024). "Epilepsy was controlled in 83.3% (five of six) of SCN1B variant patients." (PMID 38174099, 2023). "However, the β1 subunit regulates Nav1.1 sodium ion current disappearance, revealing that this SCN1B mutation is a LoF mutation, thus providing a basis for the treatment of SCN1B-related epilepsy." (PMID 38174099, 2023).
epilepsy (continued). "LOF variants in SCN1B are linked to epilepsy and cardiac arrhythmia." (PMID 35603785, 2022). "Regions of SCN1B with functionally validated epilepsy variants with references." (PMID 33841294, 2021). "SCN1B is known to be associated with atrial fibrillation, familial, 13 (#615377), Brugada syndrome 5 (#612838), developmental and epileptic encephalopathy 52 (#617350), and epilepsy with febrile seizures plus and type 1 (#604233) due to the presence of pathogenic mutations." (PMID 36959829, 2023). "The disease penetrance of SCN1B p.C121W and p.I70_E74del mutations for GEFS+ is found to be 62–76%.There is also variable expressivity, and family members that share the same SCN1B variant may be seizure-free, with febrile seizures, or with epilepsy (most frequently FS+)." (PMID 36291443, 2022). "Scn1bC89/C89 and Scn1b-null mouse CMs have increased functional expression of Ito and, similar to other model of epilepsy, both mouse strains show increased cardiac fibrosis and high propensity to pacing-induced cardiac arrhythmias." (PMID 40763036, 2025). "Nav channel mutations are related to epilepsy, including α subunits, such as Nav1.1 (SCN1A), Nav1.2 (SCN2A), Nav1.3 (SCN3A), Nav1.6 (SCN8A), and Nav1.7 (SCN9A), and the β subunit (SCN1B)." (PMID 38174099, 2023). "Except for α subunit, β subunit (Scn1b), type 2 (Scn2a), and type 8 (Scn8a) have also been used as genetic models for epilepsy in mice." (PMID 36835631, 2023). "SCN1A/SCN2A/SCN8A variant-related epilepsy was generally manifested at an earlier age, while the SCN3A/SCN9A/SCN1B variant-related subtype showed a later age at onset." (PMID 38174099, 2023). "This study investigated several genetic variants of SCN genes (SCN1A, SCN2A, SCN3A, SCN1B, SCN2B, SCN3B and SCN8A) and their association with epilepsy risk; these genes have been studied in this regard and conflicted results were reported." (PMID 35801810, 2022). "Genes potentially associated with FS-related epilepsy include SCN1A, ADGRV1, SCN1B, SCN9A, GABRG2, GABRD, and CPA6." (PMID 35813073, 2022). "We chose P10 because this developmental time point is prior to disease onset in Scn1b-null mice, and thus uncomplicated by possible secondary effects of epilepsy." (PMID 33411695, 2021). "Advanced search was done using the following keyword combinations: SCN1A mutations in epilepsy, SCN1B mutations in epilepsy, SCN2A mutations in epilepsy, SCN3A mutations in epilepsy, SCN8A mutations in epilepsy and functional studies of VGSCs in epilepsy." (PMID 33841294, 2021). "Despite this finding, the treatment of SCN1B-related epilepsy with sodium channel blockers remains inconclusive." (PMID 33841294, 2021). "Selective Scn1b deletion in PV + neurons resulted in epilepsy and 100% lethality, with disease onset displaced by one week relative to Scn1b‐/‐ mice." (PMID 32979291, 2020). "Biallelic variants in SCN1B, which encodes the voltage-gated sodium channel β1/β1B subunits, are linked to DEE52, a developmental and epileptic encephalopathy with a high risk of sudden unexpected death in epilepsy (SUDEP)." (PMID 40763036, 2025). "SCN1B is mainly involved in the pathogenesis of epilepsy, and no previous study had reported the association between SCN1B and schizophrenia for far." (PMID 38413564, 2024). "Sodium channel blockers may be effective in individuals with certain SCN1B-related epilepsies, however further studies are necessary to bolster this finding." (PMID 36291443, 2022). "Additionally two likely pathogenetic variants SCN1B (rs 150,721,582) and the KCNQ2 (rs771211103) genes have been implicated in childhood epilepsies." (PMID 35177115, 2022). "We reviewed the current clinical literature pertinent to SCN1B-related epilepsy." (PMID 36291443, 2022).
epilepsy (continued). "For SCN3A, rs16850186 and the rs72550243 of SCN1B, we declare them as genetics factors that may influence the development and progression of epilepsy in Saudi population." (PMID 35801810, 2022). "There is still sparse information on the successful treatment in SCN1B-related epilepsy." (PMID 33841294, 2021). "Our patient had no history of seizures, epilepsy, or cardiac problems, indicating that SCN1B duplication might not be associated with the patient’s clinical condition." (PMID 36959829, 2023). "Several monoallelic variants in SCN1B have been associated with febrile seizures, febrile seizures plus, GEFS+, early-onset absence epilepsy, and focal epilepsy including temporal lobe epilepsy (TLE), and patients who experience sudden unexpected death from epilepsy (SUDEP)." (PMID 36291443, 2022). "By binding to SCN1B, VPA affects voltage-gated sodium channel function; thereby blocking propagation of action potentials and preventing epilepsy." (PMID 35565292, 2022). "In mice that developed normally, conditional KO of Scn1b still resulted in severe epilepsy and SUDEP, suggesting that aberrant neuronal development does not underlie Scn1b-related epileptogenesis." (PMID 36291443, 2022). "Scn1b−/− mice model EIEE52, with spontaneous epilepsy and SUDEP in 100% of animals." (PMID 32979291, 2020). "Although abnormal brain development is a characteristic of SCN1B-associated DEE, severe epilepsy and SUDEP may not stem from the underlying impaired neurodevelopment." (PMID 36291443, 2022).